SMURF2 (SMAD specific E3 ubiquitin protein ligase 2)
Diseases named in the same sentence as SMURF2 in open-access papers (continued):
Sharing a sentence is not in itself a finding about the gene and the disease.
clear cell renal cell carcinoma (3 papers, 2021 to 2024). "In clear cell renal cell carcinoma, SMURF2 overexpression is associated with improved disease-free and overall survival rates, suggesting its prognostic value." (PMID 39697237, 2024). "Elevated SMURF2 mRNA levels have been associated with improved outcomes in clear cell renal cell carcinoma (ccRCC), suggesting its potential as a biomarker for prognosis and a therapeutic target." (PMID 39697237, 2024). "Interestingly, and the observation that increased levels of SMURF2 exhibit a favorable association with improved survival in clear cell renal cell carcinoma (ccRCC), thereby emphasizing its potential value as a biomarker." (PMID 39697237, 2024). "Specifically, elevated mRNA levels of SMURF2 have been observed to correlate with improved outcomes in clear cell renal cell carcinoma (ccRCC), suggesting a protective function it serves by destabilizing HIF1α." (PMID 39697237, 2024). "The results reinforce our conclusion regarding the ability of Smurf2 to degrade HIF-1α and suggests a potential protective role of Smurf2 in clear cell renal cell carcinoma." (PMID 34611473, 2021). "We transfected the RCC4 clear cell renal cell carcinoma line with myc-Smurf2-overexpressing plasmid." (PMID 34611473, 2021). "Overexpression of SMURF2 mRNA is correlated with improved disease-free survival and overall survival in clear cell renal cell cancer." (PMID 34611473, 2021).
glioblastoma (3 papers, 2022 to 2023). The most malignant astrocytic tumor (WHO grade IV). "Mechanistically, suppression of protein arginine methyltransferase 5 (PRMT5) attenuates the expression of RNF168 in methylthioadenosine phosphorylase (MTAP)-deficient glioblastoma cells, contributing to the destabilization of H2AX by SMURF2." (PMID 36694209, 2023). "RNF168 also interacts with another E3 ubiquitin ligase, SMURF2, to modulate the stability of H2AX in glioblastoma cells." (PMID 36694209, 2023).
ischemic stroke (3 papers, 2013 to 2022). A stroke disorder caused by obstruction of blood flow to the brain, due to thrombotic (local blood clot formation) or embolic (due to a blood clot or other material traveling from another site) event. "The present study speculated the regulatory role of Smurf2 in the degradation of ALK5 in ischemic stroke." (PMID 33815059, 2021). "Additionally, Smurf2 can enhance neuron differentiation and improve functional recovery from ischemic stroke by ubiquitinating and degrading the EZH2." (PMID 33815059, 2021). "Hence, we recommend a further experimental study on humans to determine the clinical application value of the TMAO/Smurf2/ALK5 axis in ischemic stroke." (PMID 33815059, 2021). "Besides, the implication of Smurf2 in ischemic stroke has recognized its pivotal role in mediating neuronal differentiation and functional recovery." (PMID 33815059, 2021). "Collectively, our work identifies the evolutionarily TMAO/Smurf2/ALK5 signaling as a major genetic factor in the control of reactive astrocyte proliferation and glial scar formation in ischemic stroke, thus laying a theoretical foundation for the identification of ischemic stroke." (PMID 33815059, 2021).
leukemia (3 papers, 2022 to 2025). A malignant (clonal) hematologic disorder, involving hematopoietic stem cells and characterized by the presence of primitive or atypical myeloid or lymphoid cells in the bone marrow and the blood. "Smurf2 has been implicated in the development of numerous cancer types; however, its specific role in leukemia remains elusive." (PMID 40978141, 2025). "In the current study, we demonstrated that Smurf2 inhibits cell viability and triggers cell apoptosis in leukemia cells, identifying CASC3 as a potential substrate of Smurf2." (PMID 40978141, 2025). "Collectively, these findings suggest that downregulation of Smurf2 facilitated cell proliferation and inhibited apoptosis in leukemia." (PMID 40978141, 2025). "Although Smurf2 has been extensively studied in various cancers, its role in leukemia remains to be elucidated." (PMID 40978141, 2025). "To further explore the underlying mechanism of Smurf2-mediated inhibition of cell viability in leukemia, we performed a mass spectrometry analysis in HL-60 cells after Smurf2 plasmid transfection." (PMID 40978141, 2025). "To further validate the role of Smurf2 in regulating viability of leukemia cells, we overexpressed Smurf2 in HL-60, K562, and U937 cells." (PMID 40978141, 2025). "Our findings demonstrate that upregulation of Smurf2 reduces viability of leukemia cells and induces apoptosis." (PMID 40978141, 2025). "CCK-8 assays demonstrated that overexpression of Smurf2 decreased cell viability across all three leukemia cell lines." (PMID 40978141, 2025). "The data showed that knockdown of Smurf2 prolonged the half-life of CASC3 in both leukemia cell lines." (PMID 40978141, 2025). "To explore whether the depletion of Smurf2 enhances cell viability through governing CASC3 expression in leukemia, we infected HL-60 and K562 cells with shSmurf2 and shRNA CASC3 (shCASC3)." (PMID 40978141, 2025). "Hence, Smurf2 overexpression attenuated cell viability, induced cell-cycle arrest, and stimulated apoptosis in leukemia." (PMID 40978141, 2025). "It is essential to determine whether an association between Smurf2 and CASC3 exists in leukemia patient samples." (PMID 40978141, 2025). "Collectively, our results suggest that the Smurf2/CASC3 axis may serve as a potential therapeutic target for the treatment of leukemia." (PMID 40978141, 2025). "In our work, we identified that CASC3 is a substrate of Smurf2 in leukemia cells." (PMID 40978141, 2025). "Given that Smurf2 targets multiple substrates involved in tumorigenesis, it remains to be determined whether additional critical Smurf2 substrates contribute to leukemia development." (PMID 40978141, 2025). "In conclusion, targeting the Smurf2/CASC3 axis may offer a potential therapeutic strategy for the treatment of leukemia." (PMID 40978141, 2025). "Thus, Smurf2 knockdown promotes cell viability in part via regulating the expression of CASC3 in leukemia cells." (PMID 40978141, 2025). "In this study, we investigated the function of Smurf2 in leukemia progression." (PMID 40978141, 2025). "To determine whether Smurf2 influences cell cycle in leukemia cells, we explored cell-cycle distribution in HL-60 and K562 cells following shSmurf2 infection." (PMID 40978141, 2025). "Several studies have suggested a role for Smurf2 in leukemia cells." (PMID 40978141, 2025). "Moreover, cell-cycle analysis indicated that increased Smurf2 expression triggered G0/G1 phase arrest in three leukemia cell lines." (PMID 40978141, 2025). "In conclusion, the Smurf2/CASC3 axis may act as a potential therapeutic target for leukemia therapy." (PMID 40978141, 2025). "Moreover, we observed that Smurf2 knockdown increased the expression of Bcl-2 in leukemia cells." (PMID 40978141, 2025). "Furthermore, upregulation of Smurf2 led to increased apoptosis in all three leukemia cell lines." (PMID 40978141, 2025). "However, whether Smurf2 functions redundantly or synergistically with RNF146 ligase in leukemia has yet to be determined." (PMID 40978141, 2025).
leukemia (continued). "Moreover, we identified CASC3 as a substrate of Smurf2 in leukemia." (PMID 40978141, 2025). "Hence, it is important to investigate whether schisandrin B and curcumin can modulate Smurf2 expression in leukemia." (PMID 40978141, 2025). "Notably, Smurf2 upregulation inhibited the expression of Bcl-2 in leukemia cells." (PMID 40978141, 2025). "Moreover, Smurf2 exerts its biological effects by regulation of CASC3 in leukemia." (PMID 40978141, 2025). "Strikingly, the 137–283 domain of CASC3 plays a critical role in Smurf2-mediated ubiquitination and degradation of CASC3 in leukemia." (PMID 40978141, 2025). "In the current study, we report that Smurf2 enhances CASC3 ubiquitination and degradation, thereby attenuating leukemia progression." (PMID 40978141, 2025). "However, the role of Smurf2 in leukemia development remains unclear." (PMID 40978141, 2025). "To further dissect whether CASC3 is a downstream target of Smurf2, we assessed the expression of CASC3 in leukemia cells after Smurf2 modification." (PMID 40978141, 2025). "Altogether, these findings suggest that the 137–283 domain and K254 could be critical for Smurf2-mediated ubiquitination and degradation of CASC3 in leukemia." (PMID 40978141, 2025). "Furthermore, the regulatory mechanisms controlling Smurf2 expression and its subsequent effect on CASC3 protein levels in leukemia remain unclear." (PMID 40978141, 2025).
lymphoma (3 papers, 2014 to 2018). A malignant (clonal) proliferation of B- lymphocytes or T- lymphocytes which involves the lymph nodes, bone marrow and/or extranodal sites. "Collectively, these results support the conclusion that MIR503HG promotes lymphoma cell proliferation in ALK-negative ALCL through the miR-503/Smurf2/TGFBR pathway." (PMID 29758012, 2018).
melanoma (3 papers, 2011 to 2022). A malignant, usually aggressive tumor composed of atypical, neoplastic melanocytes. "Melanoma cells resistant to the cytotoxic effects of MEK inhibitors counteracted TGF-β signaling through overexpression of the E3 ubiquitin ligase SMURF2, which resulted in increased expression of the transcription factors PAX3 and MITF." (PMID 24743024, 2014). "All melanoma cell lines exhibited elevated and rather similar levels of Arkadia and variable levels of Smurf2." (PMID 21211030, 2011). "The study also found increased SMURF2 expression in advanced stages of melanoma." (PMID 24743024, 2014).
osteosarcoma (3 papers, 2010 to 2025). A usually aggressive malignant bone-forming mesenchymal neoplasm, predominantly affecting adolescents and young adults. "Additionally, the direct binding of E3 ligases Smad ubiquitination-related factor 1 (Smurf2) with E3 ubiquitin ligase RLIM (RING finger LIM domain-binding protein) markedly enhances the response of osteosarcoma U2OS cells to TGF-β (transforming growth factor-β)." (PMID 39062505, 2024).
ovarian carcinoma (3 papers, 2022 to 2024). A malignant neoplasm originating from the surface ovarian epithelium. "Furthermore, the pivotal role of SMURF2 in the pathogenesis of ovarian cancer underlines its essential function as an E3 ubiquitin ligase for RACK1." (PMID 39697237, 2024). "This action unveils a reciprocal expression pattern between SMURF2 and RACK1, with ovarian cancer manifestations displaying lower SMURF2 levels correlating with diminished RACK1 ubiquitination." (PMID 39697237, 2024). "Elevated RACK1 levels in the absence of SMURF2 correlate with poor patient outcomes, positioning SMURF2 as a critical regulator in ovarian cancer progression." (PMID 39697237, 2024). "SMURF2 was abnormal low expression in human ovarian cancer, resulting in decreased ubiquitination of RACK1 and increased stability, which promoted OC progression, and strongly associated with poor patients’ prognosis." (PMID 37828084, 2023). "In ovarian cancer, SMURF2 acts on RACK1, an adaptor protein involved in cancer signaling." (PMID 39697237, 2024).
renal cell carcinoma (3 papers, 2010 to 2021). "Smurf2 upregulation has been associated with poor prognosis in cancers including esophageal squamous cell carcinoma and renal cell carcinoma." (PMID 20825672, 2010). "Notably, aberrant expression of Smurf2 occurs in several types of cancers, including breast, esophageal, pancreatic and renal cell carcinomas." (PMID 25191523, 2014).
bladder cancer (2 papers, 2014 to 2019). "Here, the authors show that HGF induces EMT and invasion by stabilising TGFβ receptor through inhibition of the SMURF2 ligase, and the combined blockade of MAPK and TGFβ pathways suppresses HGF-mediated bladder cancer progression." (PMID 31554791, 2019). "First, SMURF2 inhibition by c-SRC upregulates the TβR pathway by stabilising TGFβR complex a function we define to be critical for HGF-induced EMT and invasion in vitro and tumour progression in vivo in bladder cancer." (PMID 31554791, 2019). "The mRNA level of WWP1, FBW7 and SMURF2, which have been reported to interact with KLF5 and mediate the ubiquitination of KLF5, were not significantly up-regulated by curcumin in 5637 and WH bladder cancer cells." (PMID 25170806, 2014).
carcinoma in situ (2 papers, 2018 to 2019). "Our analyses revealed that in contrast to normal and carcinoma in situ tissue samples, where SMURF2 exhibited a predominantly nuclear localization, in invasive and metastatic tumors SMURF2 was mostly sequestered in the cytoplasmic compartment of BRCA cells." (PMID 31003445, 2019).
colitis (2 papers, 2024 to 2025). Inflammation of the colon. "Notably, TRM-specific deficiency of Smurf2 significantly exacerbates TRM proliferation in dextran sulfate sodium (DSS)-induced colitis and experimental autoimmune encephalomyelitis (EAE), leading to augmented autoimmune inflammation." (PMID 41271597, 2025).
diabetes (2 papers, 2018 to 2024). "This is reflected by the increased induction of chemokine transcripts by plasma of siblings with low HLA risk and individuals with diabetes, and elevated induction of regulatory transcripts (IL2RA, CBLB, SMURF1, SMURF2, SKI) by plasma of siblings with high HLA risk and unrelated control individuals." (PMID 30167736, 2018). "Taken together, our results indicate that CT can obviously improve vascular endothelial injury in Type 1 diabetes mellitus (T1DM) rats and reverse the expressions of GCH1 and Smurf2 proteins in aorta of T1DM rats." (PMID 38993132, 2024).
diffuse large B-cell lymphoma (2 papers, 2019 to 2022). "In addition, mice deficient in the E3 ubiquitin ligase Smurf2 spontaneously develop B-cell lymphomas that resemble human diffuse large B-cell lymphoma (DLBCL) with molecular features of germinal center or post-germinal center B cells." (PMID 36612252, 2022). "We previously discovered a novel circulating microRNA (miRNA) signature in a Smurf2-deficient mouse model that spontaneously develops diffuse large B-cell lymphoma (DLBCL)." (PMID 31748664, 2019).
glioma (2 papers, 2022 to 2024). A benign or malignant brain and spinal cord tumor that arises from glial cells (astrocytes, oligodendrocytes, ependymal cells). "Interestingly, the level of SMURF2 Thr249 phosphorylation is lower in GSCs compared to differentiated glioma cells, leading to increased TGF-β activity; SMURF2 Thr249 phosphorylation regulates GBM tumor growth, invasiveness, and self-renewal of GSCs." (PMID 38256140, 2024). "Although we should investigate whether SMURF2Thr249 phosphorylation has a prognostic value for glioma patients, SMURF2 could exert tumor suppressor functions in glioma pathogenesis, in which SMURF2 activity is controlled by SMURF2Thr249 phosphorylation status rather than SMURF2 expression levels." (PMID 35017630, 2022). "Our experimental findings aligned with publicly available clinical data suggest that SMURF2Thr249 phosphorylation rather than SMURF2 levels (protein and mRNA) might be associated with tumor grade and glioma stemness in humans." (PMID 35017630, 2022). "However, although SMURF2 should be assumed to play an opposite role from that of USP15, no reports have yet directly addressed the implication and underlying mechanisms of SMURF2 on the GSC phenotypes and subsequent glioma pathogenesis both in vivo and in vitro." (PMID 35017630, 2022). "SMURF2 interacts with and destabilizes H2AX, which plays a central role in DNA repair and genome stability, in glioma cells." (PMID 35017630, 2022).
intervertebral disc degeneration (2 papers, 2019 to 2021). "We have recently demonstrated that overexpression of Smurf2 under the control of type II collagen alpha 1 (Col2a1) promoter induces an intervertebral disc degeneration phenotype in Col2a1‐Smurf2 transgenic mice." (PMID 30828686, 2019). "Additionally, in an aging-induced intervertebral disc degeneration (IVDD) mice model, ectopic expression of SMURF2 accelerated proteoglycan loss and collagen fibrosis of nucleus pulposus (NP)." (PMID 35003523, 2021).
invasive ductal carcinoma (2 papers, 2014 to 2018). "In contrast, invasive ductal carcinomas showed focal or diffuse decrease in Smurf2 expression, which was observed more frequently in triple-negative tumors than in ER-positive tumors." (PMID 24485087, 2014).
lung adenocarcinoma (2 papers, 2023 to 2025). A carcinoma that arises from the lung and is characterized by the presence of malignant glandular epithelial cells. "Taken together, these results suggest that SMURF2 may function as a tumor suppressor in lung adenocarcinoma." (PMID 37497010, 2023).
metastatic tumors (2 papers, 2019 to 2022). "High Smurf2 expression in both primary and metastatic tumors was significantly associated with longer overall survival time and time to surgical failure." (PMID 35361871, 2022). "Our clinical data demonstrates that the prognosis was significantly worse in patients with low Smurf2 expression in both primary tumors and metastatic tumors compared to the prognosis of patients with high Smurf2 expression." (PMID 35361871, 2022). "Smurf2 protein expression was examined in metastatic tumors in the liver using IHC." (PMID 35361871, 2022). "Additionally, our clinical data demonstrates that the TSF was significantly shorter in patients with low Smurf2 expression in both primary tumors and metastatic tumors." (PMID 35361871, 2022). "However, analysis of Smurf2 expression levels in primary versus matching metastatic tissues did not detect significant changes in SMURF2 staining intensity, although some reduction in the percentage of SMURF2-positive cells was monitored in metastatic tumors." (PMID 31003445, 2019). "In addition, our findings show that in primary BRCA tumors SMURF2 protein levels were considerably elevated in comparison to adjacent normal tissues, although no significant changes were detected in SMURF2 levels in primary versus matching metastatic tumors." (PMID 31003445, 2019).